CGAS (cyclic GMP-AMP synthase)
Diseases named in the same sentence as CGAS in open-access papers (continued):
Sharing a sentence is not in itself a finding about the gene and the disease.
tumor (continued). "In these tumours, RAB5A induction increased CytoDR, as expected, and was associated with an elevated number of γH2AX-positive cells, and increased levels of cGAS, which display a perinuclear dotted or crescent-like appearance." (PMID 36581770, 2023). "This chronic stimulation of the cGAS-STING pathway of appropriate intensity in tumor cells may mediate tumor cells survival and metastasis." (PMID 37965570, 2023). "In contrast, the L1 repression function of nuclear cGAS might be exerted throughout the cell cycle stages, thus cGAS may serve as a tumor suppressor in these quiescent somatic cells." (PMID 38086852, 2023). "Furthermore, tumor-derived DNA can be transferred and released into the cytosol of macrophages and DCs20, which in turn, activates cGAS-STING-IRF3-induced IFN signaling and enables DCs to present tumor-antigen and prime CD8+ T cells for anti-tumor immunity." (PMID 37833461, 2023). "Together with previous results, we suggested that DNA damage caused by Cdk4-deficiency could activate cGAS-STING pathway, stimulate type I IFN and enhance anti-tumor immunity." (PMID 37833461, 2023). "Furthermore, STING-NP-treated tumor-bearing mice resulted in >50% and 80% reduction in tumor burden by cGAS-STING signaling in melanoma and breast adenocarcinoma models." (PMID 37020586, 2023). "Furthermore, SENP3 activity enhances anti-tumor immune responses, a mechanism that is facilitated by cGAS in mice." (PMID 38139802, 2023). "Finally, ionizing radiation-mediated tumor regression depends on the cGAS–STING-dependent cytosolic DNA sensing pathway through the internalization of tumor-cell-derived DNA in dendritic cells, which drives the adaptive immune response to radiation." (PMID 37175853, 2023). "Therefore, the cGAS-STING signalosome was proposed to be contributed to anti-tumor immunity by inducing an immune suppressive TME." (PMID 37190141, 2023). "Apart from tumor-intrinsic cGAS-STING induction that could contribute to a beneficial therapeutic outcome, a critical event here is the production and release of cGAS-STING agonists that stimulate immune cells." (PMID 38022587, 2023). "Similarly, while STING and cGAS expression have been found to be epigenetically silenced in some tumours, many cancers show normal or elevated cGAS and STING expression." (PMID 37534795, 2023). "Thus, DNA released from dying tumor cells can be taken up by MICs to activate the cGAS/STING pathway." (PMID 37380989, 2023). "Alternatively, DNA may also be released from dying tumor cells, activating the cGAS/STING pathway in a tumor-extrinsic fashion." (PMID 36394642, 2023). "Pyroptosis and cGAS–STING pathways play an essential role in enhancing tumor immunotherapy." (PMID 37342347, 2023). "In an in vivo tumor model, Mn administration reduced tumor burden, whereas cGAS knock-out mice and STING-deficient mice did not respond to Mn." (PMID 38132161, 2023). "Moreover, Mn2+ is a powerful cGAS activator to enhance STING-mediated type I IFN response in both tumor cells and DCs, involving STING, tank-binding kinase 1 (TBK1), and interferon regulatory factor 3 (IRF-3) phosphorylation 25,26." (PMID 37221157, 2023). "Approximately 55% of metastatic tumor-derived cells were reported to be cGAS positive." (PMID 37965570, 2023). "Conversely, tumor cells can also escape the immune surveillance mediated by the cGAS–STING pathway." (PMID 37686127, 2023). "Hence, the cGAS/STING pathway functions in tumor surveillance and in the immunological response to cancer therapy by responding to an accumulation of unrepaired DNA." (PMID 37259920, 2023). "Importantly, knocking down cGAS or STING in DCs reduced the cross‐priming capacity of DCs for tumor antigen‐specific CD8+ T cells." (PMID 37786300, 2023). "The activated cGAS‐STING signaling can occur in both tumor cells and immune cells, but it may have unique functions." (PMID 37986544, 2023).
tumor (continued). "In addition, emerging evidence suggests the pro-tumor roles of the cGAS-STING pathway in tumor initiation, development, and metastasis." (PMID 37783727, 2023). "In further studies, cGAS-STING was found to have a tumor-suppressive effect." (PMID 36936940, 2023). "Therefore, our findings of frequent STING downregulation and cGAS upregulation in OSA cell lines are in line with studies in other tumor types." (PMID 37079538, 2023). "Mn2+ is a cGAS-STING agonist that can significantly enhance anti-tumor immunity." (PMID 37600809, 2023). "Furthermore, olaparib-induced activation of the cGAS-STING pathway evokes an antitumoral immune response in bulk tumour cells that is a critical component for an effective treatment response." (PMID 36980782, 2023). "The high expression of tumor cell-intrinsic cGAS-STING might contribute to the activation of immune cells in the TME, resulting in better prognosis for ICI treatment in dMMR/MSI-H CRC." (PMID 37345163, 2023). "Furthermore, NEAT1 contributes to the promotion of tumor growth by hampering cytotoxic T cell-mediated immunity, primarily through the downregulation of the stimulator of interferon genes, cyclic GMP-AMP synthase." (PMID 38066437, 2023). "Lactobacillus rhamnosus GG (LGG) improving immune checkpoint blockade was associated with STING pathway.Oral administration of LGG enhanced the anti-tumoral effect of PD-1 immunotherapy by increasing tumor-infiltrating DCs and T cells through the cGAS-STING pathway-mediated IFN production." (PMID 37781354, 2023). "For immune-checkpoint anti-tumor therapies, the cGAS-STING pathway is crucial." (PMID 38139802, 2023). "In tumor cells, activating the cGAS-STING pass-through may inhibit the development of early tumors by upregulating type I IFN and other inflammatory genes." (PMID 36936940, 2023). "Therefore, further research is required to explore the role of the cGAS-STING pathway in different tumor-infiltrating immune cells in specific tumors." (PMID 37153627, 2023). "However, patient benefits often remain limited since cGAS/STING signaling is silenced in many tumor entities or antagonized, e.g., by the human papillomavirus (HPV)-associated oncoprotein E7 in HPV16-positive oropharyngeal carcinomas." (PMID 37834346, 2023). "Thus, it is essential to elucidate the regulatory mechanisms of the cGAS-STING signaling pathway in tumor cells." (PMID 37920470, 2023). "While it is evident that stimulation, particularly in the acute setting, of STING in antigen-presenting cells is tumour suppressive, the role of cGAS–STING signalling as a result of constitutive CIN-driven stimulation in the tumour environment is not as clearly defined." (PMID 36876871, 2023). "Besides cell senescence and chronic inflammation, cGAS/STING signaling in the cancer cell was also proposed to induce anti-tumor immunity." (PMID 37180110, 2023). "Thus, our study supports that cGAS‐dependent signaling is acquired during tumorigenesis and that cGAS and DNA‐PK activities should be analyzed concertedly to predict the impact of strategies aiming to boost tumor immunogenicity." (PMID 36574362, 2023). "In addition, recent studies indicate that ENPP1 is also involved in cGAS-STING signaling which plays an important role in the anti-tumor immune response." (PMID 36761762, 2023). "Epigenetic silencing of STING and cGAS inhibited tumor cell death and anti-tumor response." (PMID 37781354, 2023). "The activation of the cGAS-STING pathway in tumor cells in response to cisplatin suggests that this signaling pathway may play an important role in tumor progression." (PMID 37569723, 2023). "This raises the first question of whether cGAS, as a major recognition factor for MN and mtDNA, is involved in mediating tumor metastasis and/or pro-survival." (PMID 37569723, 2023). "However, CIN facilitates tumor cell survival by triggering IL-6-STAT3-mediated signaling through the cGAS-STING and NF-κB pathways." (PMID 37122745, 2023).
tumor (continued). "In addition to these tumor‐intrinsic parameters, the diversity of cells composing the tumor microenvironment and their differential expression of cGAS and/or STING are also determinant for tumor fate." (PMID 36574362, 2023). "Moreover, when tumor cells sustain DNA damage response pathways or lack cGAS, the combination of STING agonists and PARP inhibitors can be utilized to further bolster anti-tumor immunity, effectively broadening the applicability of PARP inhibitors." (PMID 37920470, 2023). "In this study, we focused on the relationship between the overexpression of IDH3α and the acidic tumor microenvironments and confirmed whether the inhibition of IDH3α could sensitize tumors to chemoimmunotherapy by activating the cGAS–STING pathway." (PMID 36980689, 2023). "Persistent DNA-leakage-mediated activation of cGAS-STING may have effects both on the cancer cells that display CIN as well as the immune cells that infiltrated the tumour, as cGAS will enhance the inflammatory response of the cancer cells." (PMID 38067140, 2023). "The identification of strategies that restore or reactivate tumor cell–intrinsic cGAS/STING signaling may be useful to enhance cancer treatment efficacy." (PMID 37888903, 2023). "The cGAS-STING pathway is critical for anti-tumour immunity via the recognition of damage-associated molecular patterns (DAMPs), primarily tumour-derived DNA, therefore inhibition of C5aR2 may amplify the host innate immune response to drive tumour clearance." (PMID 38067135, 2023). "Moreover, GPC3144‐152‐induced CTL recruitment and infiltration into the tumor microenvironment were dependent on activation of the intratumoral cGAS/STING pathway." (PMID 37986544, 2023). "Since cGAS-STING-mediated IFN signaling can limit tumor growth, tumor cells may silence this pathway to evade immune surveillance." (PMID 37122745, 2023). "Upon DNA damage and spillage, cGAS recognizes and activates the expression of interferon and other immune factors, which, in conjunction with anti-inflammatory cytokine release, can recruit lymphocyte infiltration to effectuate tumor cell eradication." (PMID 37920470, 2023). "For tumor cells in particular, activation of cGAS-STING pathway may also lead to different outcomes." (PMID 37670034, 2023). "As EZH2 is a methyltransferase, EZH2 and USP7 may regulate the levels of methylation and ubiquitination of cGAS, which leads to the production of inflammatory factors in tumor cells after the activation of cGAS." (PMID 35163710, 2022). "However, prolonged type I IFNs signaling induced by the cGAS-STING pathway can cause immune dysfunction and promote tumor development." (PMID 35209954, 2022). "Moreover, tumor-derived exosomes produced following RT can also transfer immunostimulatory RNA to DCs and stimulate the cGAS-STING-dependent activation of type I IFNs." (PMID 36139006, 2022). "Thus, the cGAS-STING-TBK1 DNA sensing cascade is traditionally considered as a measure of tumor suppression." (PMID 35992877, 2022). "The cGAS/STING signaling pathway plays critical role in tumor suppression and immune surveillance." (PMID 35835756, 2022). "Although this observation was explained by the passage of cGAMP from cancer cells to neighboring astrocytes through gap junctions, it is possible that in an immunoprivileged microenvironment, cGAS-STING activation cannot elicit an antitumor response but instead supports the survival of tumor cells." (PMID 36003402, 2022). "The cGAS-STING pathway plays an anti-tumor or pro-tumor role." (PMID 36353640, 2022). "Though further study is needed to confirm this mechanism, it is also thought that cytosolic DNA from tumor cells can be transferred to the cytosol of immune cells to induce cGAS/STING signaling and enhance antigen presentation and cross-priming in DCs and T cells, respectively." (PMID 36276148, 2022).
tumor (continued). "Moreover, elevated expression of microRNA (miR)-93/25 observed in breast cancer facilitates tumor evasion from immune surveillance and destruction partially through downregulating cGAS expression." (PMID 36139387, 2022). "Whether tumors can afford cGAS–STING pathway activation by generating a T-cell-rich tumor microenvironment has therapeutic implications." (PMID 35267494, 2022). "The cGAS-STING pathway is the most compelling activation pathway in tumor innate immunity." (PMID 35493527, 2022). "This suggests that cGAS inhibition in the presence of DNA-damaging agents may result in reduced cell death in normal cells while sensitizing tumor cells to such therapy." (PMID 35602594, 2022). "The signatures of tumor-restrain CAFs were expressed in tumors with cGAS-STING signaling." (PMID 35773436, 2022). "Translational research using hot tumors revealed that the spontaneous MSA-specific CD8+ T cell infiltration into tumors is facilitated by the recognition of tumor-derived DNA by the cytosolic cGAS-STING signaling pathway in tumor-infiltrating conventional type 1 dendritic cells (cDC1 TIDCs)." (PMID 35432377, 2022). "Furthermore, tumor-derived DNA or cGAMP activates DCs via the cGAS–STING pathway, inducing the production of type I IFNs that enhance the cross-presentation ability of DCs and improve tumor clearance via adaptive immunity." (PMID 35734577, 2022). "Indeed, cumulative evidence implied that sustained activation of cGAS/STING signaling pathway can create an immune suppressive TME that favors tumor progression." (PMID 36588690, 2022). "We confirmed that cGAS signaling mediates the mitotic SENP3 activation-induced anti-tumor immunity." (PMID 35869062, 2022). "On the contrary, stimulation of the cGAS-STING pathway may result in tumor development and metastasis as well." (PMID 35889509, 2022). "Such a signature could reshape tumor immunity in the ccRCC microenvironment by activating antigen presentation and cGAS-STING signaling." (PMID 36581992, 2022). "All these results suggested that cuprotosis could enhance tumor immunity although cGAS-STING signaling in ccRCC." (PMID 36581992, 2022). "A key mechanism of action of pyridostatin is activation of cGAS/STING‐dependent innate immune responses, which may underlie its efficacy against BRCA1/2‐mutated tumours in vivo." (PMID 35107878, 2022). "Interestingly, Topotecan, a clinically used Top1 poison, can activate dendritic cells of tumour-bearing mice as exosomes released by the treated tumours are incorporated by dendritic cells, which then triggers the cGAS/STING signalling pathway." (PMID 36114513, 2022). "In particular, irradiated tumor cells are recognized by the cGAS-STING pathway in DCs." (PMID 35806328, 2022). "Our work thus supports that a link exists between the innate and the adaptive immune response, where cancer-associated CIN occurring in cancers with functional cGAS-STING pathway results in activation of an IFN response and recruitment of immune cells to the local tumor microenvironment." (PMID 36923311, 2022). "Thus, the tumor microenvironment should be carefully monitored during the therapeutic induction of cytosolic DNA accumulation and cGAS/STING pathway activation using DDRi therapy." (PMID 36276148, 2022). "Furthermore, evidence suggests that the degradation of cytosolic dsDNA induced by radiation is the trigger for type I IFN secretion in tumor cells; the tumor cell-intrinsic activation of type-I IFNs was also confirmed to be dependent on the cGAS-STING pathway." (PMID 35292881, 2022). "Taken together, inhibition of cGAS-STING pathway could impair the expression of IFN-β in the irradiated tumor cells, which resulted in the decrease of IFN-γ production in the bystander T lymphocytes." (PMID 35847556, 2022). "The nanoplatform could release Mn2+ from MnIIIPC@DTX@PLGA@Mn2+@HA(MDPMH) and probably activate tumor immunity through cGAS-STING and chemotherapy, respectively." (PMID 35308235, 2022).
tumor (continued). "MnIIIPC induced much heat in tumor cells under the irradiation of an 808-nm near-infrared laser; Mn2+ deposited on the surface of nanocarriers could activate tumor immunity through cGAS-STING." (PMID 35308235, 2022). "Therefore, the DDR pathway can inhibit immune response by reducing the production of tumor neoantigens and inhibiting the CGAS-STING signaling pathway, which is consistent with our findings of DCS2 clusters." (PMID 36478716, 2022). "Thus, activating the cGAS-STING signaling pathway in tumor cells can significantly enhance tumor immunotherapy effects." (PMID 35185917, 2022). "By elegant step-by-step approaches, the authors demonstrated that TTFields promote the production of immune-stimulating proinflammatory and interferon type 1 cytokines in tumor cells in a cGAS/STING- and AIM2 inflammasome–dependent mechanism, thereby activating the immune system." (PMID 35426370, 2022). "Therefore, it is possible that exosomes containing tumor-derived DNA can induce the activation of the cGAS-STING pathway in irradiated HNSCC cells." (PMID 35563740, 2022). "Researchers found that tumor-derived DNA and cGAMP activate the cGAS-STING pathway in DCs via an unknown mechanism, which in turn performs cross-presentation to DCs and recruits CD8+ T cells for direct, non-spontaneous tumor elimination." (PMID 36231006, 2022). "Mechanistic studies revealed that cGAMP promotes the maturation of dendritic cells in a cGAS–STING-dependent manner and facilitates the presentation of tumor-associated antigens, thus promoting the killing of tumor cells by tumor-specific antigen-activated CD8+ T cells." (PMID 35536585, 2022). "The expression of NKG2DL in tumor cells may be the result of cGAS/STING pathway-induced IFN-1 expression." (PMID 36071479, 2022). "The initiation, transmission, and execution of the cGAS–STING pathway can take place among different cell types within the TME and thus cGAS–STING may play opposing roles in driving tumor progression in addition to its tumor cell-intrinsic role." (PMID 35325182, 2022). "Targeting BER factors may increase cytosolic DNA and enhance cGAS-STING signaling which could increase the immunogenicity of a tumor’s microenvironment." (PMID 36624848, 2022). "It has recently been shown that the ZBP1-MLKL necroptotic cascade induces cytoplasmic DNA accumulation in irradiated tumor cells and, in turn, autonomously activates cGAS-STING signaling, thus creating a positive feedback loop between these two pathways to drive persistent inflammation." (PMID 36089194, 2022). "On the other hand, tumor MPs contain fragments of tumor cell mitochondrial and genomic DNA, which may activate the cGAS-STING pathway for type I interferon induction." (PMID 34983944, 2022). "The lack of responsiveness of Ifne to classic type I IFN inducers (such as TLR and cGAS-STING agonists) highlights its potential function as a constitutive enforcer of tumor immune surveillance, perhaps mirroring its only known role in mediating mucosal immunity." (PMID 36344707, 2022). "In addition, Ki67, SOX2 and N‐cadherin were significantly downregulated in the PCAT1‐depleted tumours, while cGAS, STING and E‐cadherin were upregulated." (PMID 35415876, 2022). "Various mechanisms are engaged in the tumor-promoting function of cGAS and STING." (PMID 35325182, 2022). "It is of great interest to examine whether ARIH1 also exerts anti-tumor activity through promoting ISGylation and activation of cGAS." (PMID 36217001, 2022). "Additionally, STING is frequently lost during tumor progression, and loss of STING/cGAS correlates with poor survival." (PMID 35099823, 2022). "Therefore, valuable therapeutic targets for cGAS/STING pathway activation represented a potential strategy with major implications for anti‐tumour and cancer immunotherapy." (PMID 35415876, 2022).